FBXO43 (F-box protein 43)
Description:
Required to establish and maintain the arrest of oocytes at the second meiotic metaphase until fertilization. Acts by inhibiting the anaphase-promoting complex/cyclosome (APC/C) ubiquitin ligase. Probably recognizes and binds to some phosphorylated proteins and promotes their ubiquitination and degradation. Plays a vital role in modulating the ubiquitilation of CCNB1 and CDK1 during gametogenesis.
Synonyms: EMI2; Fbx43; ERP1; OOMD12; OZEMA12; SPGF64
Tractability: PROTAC: UniProt records ubiquitination sites on it; ubiquitination databases record sites on it.
Gene: Protein-coding gene on chromosome 8 (100,133,351 to 100,145,817, reverse strand). Ensembl gene ENSG00000156509.
Subcellular location (Human Protein Atlas): Cytosol
Gene Ontology:
Molecular function: protein binding; zinc ion binding
Biological process: negative regulation of cell cycle process; negative regulation of meiotic nuclear division; regulation of mitotic nuclear division; SCF-dependent proteasomal ubiquitin-dependent protein catabolic process; cellular response to nerve growth factor stimulus; protein ubiquitination
Cellular component: nucleus; SCF ubiquitin ligase complex
Genetic constraint (gnomAD): Loss-of-function variants: 15 observed, 50.86 expected, observed/expected ratio (o/e) 0.29, 90% interval 0.2 to 0.45. The upper end of that interval is the gene's LOEUF score, 0.45, which puts it in group 2 of 6, group 1 being the genes least tolerant of losing a copy. Missense variants: 693 observed, 800.71 expected, observed/expected ratio (o/e) 0.87, 90% interval 0.81 to 0.92. Synonymous variants: 291 observed, 292.98 expected, observed/expected ratio (o/e) 0.99, 90% interval 0.9 to 1.09.
Homologues: Orthologues: chimpanzee FBXO43 (99% identical), pig FBXO43 (79% identical), dog FBXO43 (77% identical), rabbit FBXO43 (75% identical), guinea pig FBXO43 (68% identical), mouse Fbxo43 (62% identical), rat Fbxo43 (62% identical), tropical clawed frog fbxo43 (43% identical), zebrafish fbxo43 (27% identical), Drosophila melanogaster Rca1 (12% identical). Paralogues in human: FBXO5 (18% identical).
Diseases named in the same sentence as FBXO43 in open-access papers:
FBXO43 is named in the same sentence as 19 diseases in open-access papers, as found by Europe PMC text mining. Sharing a sentence is not in itself a finding about the gene and the disease. The quoted sentences say what the papers report.
breast carcinoma (5 papers, 2021 to 2023). "It has been reported that FBXO43 is overexpressed in breast cancer and is associated with poor survival and a high risk of metastasis." (PMID 37250703, 2023). "For example, FBXO43 upregulation is associated with malignant clinical features such as tumor grade, tumor size, and lymph node metastasis and may predict poor prognosis in breast cancer patients." (PMID 36765911, 2023). "Our previous study on breast cancer suggests that FBXO43 is overexpressed in breast cancer and is significantly related to a worse prognosis." (PMID 37250703, 2023). "Knockdown of the FBXO43 gene decrease cell viability and proliferation in breast cancer cells, suggesting a pro‐tumorigenic role." (PMID 36710413, 2023). "Bioinformatical analyses have recently validated the aberrant expression, prognostic values, and functions of FBXO43 in breast cancer, as well as the potential oncogenic roles of FBXO43 in gastric cancer and HCC." (PMID 36765911, 2023). "Our recent study has demonstrated that FBXO43 knockdown significantly inhibits breast cancer cell growth, and prevents the development of a xenograft breast cancer model." (PMID 37250703, 2023). "Knockdown of FBXO43 can significantly inhibit the development of breast cancer in vivo and in vitro." (PMID 37250703, 2023). "To better understand the pathophysiological functions of the identified F-boxes (FBXO43, FBXO15, and CCNF) in BRCA, we performed specific-RNAi knockdown in breast carcinoma cells to assess the potential loss/gain-of-functions." (PMID 34201347, 2021). "Downregulation of FBXO43 has been shown to significantly suppress the malignant phenotypes of breast cancer cells, which may be dependent on proliferating cell nuclear antigen (PCNA) degradation and inactivation." (PMID 36765911, 2023). "It was found that down-regulation of FBXO43 could inhibit the proliferation, migration and invasion of HCC cells, revealing the pro-tumor effect of FBXO43, consistent with its role in breast cancer." (PMID 37250703, 2023). "The function and regulatory mechanism of FBXO43 in breast cancer (BC) are still unclear." (PMID 34645483, 2021). "Early mitotic inhibitor 2 (EMI2), a translation product of FBXO43, is an unfavorable prognostic biomarker in breast cancer patients." (PMID 36710413, 2023). "Interestingly, among all 71 F-box family members, there are four F-boxes (FBXO43, FBXO15, FBXL8, and CCNF) with significantly upregulated mRNA levels in breast carcinoma tissues." (PMID 34201347, 2021).
hepatocellular carcinoma (3 papers, 2020 to 2023). A malignant tumor that arises from hepatocytes. "The present study investigates the expression, function, and underlying mechanism of FBXO43 in hepatocellular carcinoma (HCC)." (PMID 36765911, 2023). "A previous study has shown that the mRNA level of FBXO43 is dramatically upregulated in hepatocellular carcinoma tissues than in normal tissues, and elevated FBXO43 expression indicates a poor prognosis in patients with hepatocellular carcinoma." (PMID 32754194, 2020).
cholangiocarcinoma (2 papers, 2021 to 2023). A carcinoma that arises from the intrahepatic biliary tree (intrahepatic cholangiocarcinoma) or from the junction, or adjacent to the junction, of the right and left hepatic ducts (hilar cholangiocarcinoma). "A recent study suggested that FBXO43 promotes the progression of cholangiocarcinoma through the PI3K/Akt signaling axis." (PMID 36937431, 2023).
female infertility (2 papers, 2022 to 2023). Diminished or absent ability of a female to achieve conception. "Moreover, we will add newly found female infertility pathogenic genes such as MEI1 and FBXO43." (PMID 35620457, 2022).
gastric cancer (2 papers, 2023). A primary or metastatic malignant neoplasm involving the stomach. "Bioinformatics analysis revealed that FBXO43 was upregulated in gastric cancer and HCC." (PMID 36765911, 2023).
infertile (2 papers, 2022 to 2023). "Even a single homozygous mutation in the FBXO43 gene can result in infertility, teratozoospermia, and non‐obstructive azoospermia in male humans." (PMID 36710413, 2023).
liver cancer (2 papers, 2021 to 2023). An epithelial or non-epithelial malignant neoplasm that arises from the liver. "FBXO43 knockdown attenuates the growth of liver cancer cells." (PMID 36710413, 2023).
teratozoospermia (2 papers, 2022 to 2023). "Several teratozoospermia-associated gene mutations, including F-box only protein 43 (FBXO43), armadillo repeat-containing protein 2 (ARMC2), SEPTIN12, and AGBL carboxypeptidase 5 (AGBL5), have been identified by measuring exonic mutations in blood samples using whole exome sequencing technology." (PMID 36292606, 2022).
chronic hepatitis (1 paper, 2023). An active inflammatory process affecting the liver for more than six months. "Receiver operating characteristic analysis of F-box protein 43 promoter methylation levels yielded an area under curve (AUC) of 0.793 with 76.42% sensitivity and 68.35% specificity when differentiating HCC from chronic hepatitis." (PMID 38029156, 2023).
chronic hepatitis B (1 paper, 2023). "Relative mRNA expression levels of F-box protein 43 in HCC PBMCs were significantly higher than those in chronic hepatitis B (P < 0.001) and healthy control PBMCs (P < 0.001)." (PMID 38029156, 2023). "F-box protein 43 promoter methylation levels were significantly lower in HCC PBMCs than the chronic hepatitis B (P < 0.001) and healthy control PBMCs (P < 0.001)." (PMID 38029156, 2023). "In this study, we analyzed expression levels of FBXO43 to infer promoter methylation levels in PBMCs among patients with HBV-associated HCC, chronic hepatitis B (CHB), and healthy controls (HCs), as well as the clinicopathological features." (PMID 38029156, 2023).
Fanconi anemia (1 paper, 2023). Fanconi anemia (FA) is a hereditary DNA repair disorder characterized by progressive pancytopenia with bone marrow failure, variable congenital malformations and predisposition to develop hematological or solid tumors. "The results showed that FBXO43 and its co‐expressed genes were mainly involved in DNA replication, cell cycle checkpoint, mitotic cell cycle phase transition, Fanconi anemia pathway, homologous recombination, and so on." (PMID 36710413, 2023).
male infertility (1 paper, 2016). The inability of the male to effect fertilization of an ovum after a specified period of unprotected intercourse. "Validation of class II high-impact variants within SPATA31E1, OVGP1, FOXP1, FBXO43 indicate further putative loci for stallion fertility, however the consequences of mutations on male infertility in human and mice are not yet known." (PMID 27079378, 2016).
testicular germ cell tumor (1 paper, 2023). A germ cell tumor arising from the testis. "FBXO43 RNA was downregulated only in testicular germ cell tumors (p < 0.05)." (PMID 36710413, 2023).
cancer (8 papers, 2020 to 2023). A tumor composed of atypical neoplastic, often pleomorphic cells that invade other tissues. "The expression profile, prognostic value, biological functions, and underlying mechanism of its involvement of FBXO43 were explored based on TCGA, Gene Expression Omnibus (GEO), LinkedOmics, and Cancer Dependency Map (DepMap)." (PMID 36710413, 2023). "Ultimately, advanced tumor TNM stage, poor histological differentiation, and high expression of FBXO43 predicted a higher risk of decreased OS, and earlier carcinoma recurrence (p < 0.05)." (PMID 36710413, 2023). "Furthermore, regarding the 93 patients with HCC, upregulated expression of the FBXO43 protein was associated with decreased OS and a much earlier carcinoma recurrence after radical surgery." (PMID 36710413, 2023). "The role of FBXO43 and the underlying mechanism in cancer are largely unknown." (PMID 36765911, 2023). "Overexpression of FBXO43 protein was significantly associated with advanced TNM stage, large tumor size, lymphatic invasion, distant metastasis, earlier cancer recurrence, and decreased overall survival after radical surgery (p < 0.05)." (PMID 36710413, 2023). "FBXO43 (F-box Protein 43), also called EMI2 (endogenous meiotic Inhibitor 2), many studies have shown that this molecule is closely related to a variety of cancers." (PMID 38283345, 2023). "Our study revealed that high expression of FBXO43 RNA or protein predicted a higher risk of HCC, decreased OS, and earlier carcinoma recurrence." (PMID 36710413, 2023). "Knockdown of FBXL8 and FBXO43 reduced cancer cell viability and proliferation, suggesting their pro-tumorigenic roles." (PMID 34201347, 2021). "Similar to FBXL8, the knockdown of FBXO43 reduced cancer cell viability and proliferation, suggesting its pro-tumorigenic role." (PMID 34201347, 2021). "Although the role of FBXO43 in biological processes has been primarily revealed in the negative regulation of meiosis II metaphase, the FBXO43 upregulation and oncogenic functions in carcinogenesis have recently been reported in several cancers." (PMID 36765911, 2023). "FBXO43, a member of F-box proteins involved in the occurrence and development of many cancers by regulating cell proliferation, apoptosis, invasion, and metastasis, has been initially demonstrated as an inhibitor of APC/C to ensure the normal progress of the meiotic division." (PMID 36937431, 2023). "In this study, we retrospectively profiled the transcriptome of BRCA tissues and found a notable upregulation of four SCFF-box E3 ligases (FBXL8, FBXO43, FBXO15, and CCNF) in the carcinoma tissues." (PMID 34201347, 2021). "We found that the association between EMI2 (FBXO43) and cancer was not common in the literature." (PMID 34933678, 2021).
tumor (6 papers, 2021 to 2023). "High expression of the FBXO43 protein was strongly associated with large tumor size, advanced TNM stage, lymphatic invasion, distant metastasis, and tumor recurrence." (PMID 36710413, 2023). "FBXO43 overexpression was strongly associated with larger tumor size, advanced tumor–nodule–metastasis (TNM) stage, lymphatic invasion, advanced T stage, and advanced N stage (p < 0.05)." (PMID 36710413, 2023). "Increased expression of FBXO43 was associated with late stage of HCC patients (including tumor grade, T and TNM stage)." (PMID 37250703, 2023). "For this study, we constructed lentiviral vectors containing shRNA targeting FBXO43 and transfected human BC cells with lentivirus to elucidate the biological functions of FBXO43 in BC and the underlying mechanism by which FBXO43 regulates tumor growth." (PMID 34645483, 2021). "Analysis of HCC data in TCGA database revealed overexpression of FBXO43 in tumor tissues compared to normal tissues." (PMID 37250703, 2023). "Surprisingly, FBXO43 RNA was significantly overexpressed in tumor tissues compared to that in matched normal tissues in 23 malignancies, including liver HCC (p < 0.05)." (PMID 36710413, 2023). "Consistent with a study of gene co-expression network analysis in HCC, we found that the mRNA expression level of FBXO43 was significantly increased in 374 HCC tumor tissues compared with 50 normal tissues in the TCGA database." (PMID 36937431, 2023). "FBXO43 is overexpressed in HCC, and is linked to late tumor stage, worse prognosis and tumor immunosuppression." (PMID 37250703, 2023). "Based on TCGA data, most malignant tumors, including HCC, FBXO43 RNA expression was significantly higher expressed in tumor tissues than in normal liver tissues." (PMID 36710413, 2023). "In comparison to normal tissues, FBXO43 is overexpressed in HCC tissue, and high FBXO43 expression is linked to late T stage, TNM stage and tumor grade." (PMID 37250703, 2023). "As for the roles of FBXO43 in tumors, a previous study reported that elevated expression of FBXO43 was correlated with tumor size, lymph node metastasis, and poor survival in BC patients." (PMID 34645483, 2021). "All the findings demonstrated that downregulation of FBXO43 inhibited the tumor growth of BC by limiting its interaction with PCNA." (PMID 34645483, 2021). "The expression level of FBXO43 was positively associated with T1-3, stage I-III and tumor grade." (PMID 37250703, 2023). "Next, to further elucidate the mechanism by which FBXO43 affect cell functions in BC, we conducted a Co-IP assay and found that FBXO43 could regulate tumor growth by interacting with PCNA." (PMID 34645483, 2021). "Therefore, to further validate the function of FBXO43 in BC, we estimated the expression level of FBXO43 by TCGA analysis and found that the expression level of FBXO43 was significantly higher in tumor tissues than in adjacent normal tissues in BC patients." (PMID 34645483, 2021). "Additionally, an in vivo experiment demonstrated that the tumor size and weight were significantly suppressed by FBXO43 knockdown." (PMID 34645483, 2021). "In our study, we observed that FBXO43 was involved in tumor growth and interacted with PCNA in BC." (PMID 34645483, 2021). "Downregulation of FBXO43 inhibits the BC tumor growth by limiting its interaction with PCNA." (PMID 34645483, 2021). "Downregulation of FBXO43 inhibits the tumor growth of BC by limiting its interaction with PCNA." (PMID 34645483, 2021). "Then, univariate and multivariate regression analyses revealed that the tumor TNM stage, degree of histological differentiation and FBXO43 expression were independent prognostic factors affecting OS and DFS." (PMID 36710413, 2023). "Multivariate Cox regression analysis showed that FBXO43 mRNA expression levels, UICC tumor stage, resection status, and adjacent inflammation were independent risk factors for OS of HCC patients." (PMID 36937431, 2023).
tumor (continued). "After univariate Cox regression, FBXO43 mRNA expression levels, UICC tumor stage, distant metastasis, UICC stage, vascular invasion, resection status, and adjacent inflammation were defined as potential risk factors for OS." (PMID 36937431, 2023). "Moreover, as the expression of FBXO43 increased in HCC, more Tregs and neutrophils were found to infiltrate the tumor tissue." (PMID 37250703, 2023). "Furthermore, the FBXO43 expression was significantly higher in HCC tissues with advanced T stage, late tumor grade, and higher serum alpha fetoprotein (AFP) level." (PMID 36765911, 2023).
FBXO43 also shares sentences with these, for which no sentence is quoted: Azoospermia (1 paper); bile duct cancer (1); infection (1); metastasis (1).